MMP9 (matrix metallopeptidase 9)
Diseases named in the same sentence as MMP9 in open-access papers (continued):
Sharing a sentence is not in itself a finding about the gene and the disease.
tumor (continued). "In contrast, MMP-9 and MMP-13 were expressed mainly in the healthy skin adjacent to the tumor." (PMID 34204372, 2021). "Results demonstrated that MMP9 expression in GBM, KIRC, LUSC, COAD and BLCA were significantly higher than normal samples, indicating the expression of MMP9 in tumor samples could be differentiated significantly from normal samples (P < 0.01)." (PMID 34261456, 2021). "Here, in MCF-7 cells, digestion of NETs with DNase did not significantly impact tumor cell migration or MMP9 gene expression, rendering DNA integrity to be dispensable in the effect of NETs over MCF-7 cells." (PMID 34835236, 2021). "Ex vivo fluorescence scanning, histological and Immunofluorescence analyses of PRISM distribution in tumor-bearing and healthy lung tissues revealed tumor-specific sensor accumulation, suggesting that the pH-selective targeting of PRISM via pHLIP enhanced on-target MMP9 cleavage." (PMID 34267368, 2021). "Also, CXCL5 promotes tumor angiogenesis, and new blood vessels act as tumor metastasis channels; CXCL5/CXCR2 can release matrix metalloproteinase-9 (MMP-9), destroys endothelial cells and matrix barrier, and promotes tumor metastasis." (PMID 33869023, 2021). "Moreover, we have investigated the stromal score, immune score, and tumor purity of five subtypes, along with the estimate score of MMP1, MMP2, MMP9, MMP12, MMP13 in five subtypes of BRCA." (PMID 35069702, 2021). "Subsequently, tumor metastasis-related proteins MMP-2 and MMP-9 were determined." (PMID 34539408, 2021). "Noteworthy, we found a dramatic upregulation of MMP9 in MSTO cells from MCS–monocytes coculture, suggesting that Mo-TAMs might enhance the invasive ability of tumor cells by favoring the expression of the ECM degrading enzyme." (PMID 33922336, 2021). "Intriguingly, through injecting KYSE-30 cells with OV-TEAD4 transfection or in combination with shRNA-SGK1 transfection into nude mice, we found that SGK1 silencing markedly interfered with the effects of TEAD4 overexpression on tumor volume and the expression of Ki67 and MMPs (MMP2 and MMP9)." (PMID 33517828, 2021). "MMP-9 induces the cleavage of laminin and collagen within the basement membrane and ECM, which promotes the movement of endothelial cells and pericytes and ECM remodeling that is critical for tumor angiogenesis." (PMID 34327245, 2021). "In addition, M2-like macrophages and tumor cells secrete MMP-9 and VEGF, which can also promote tumor cell metastasis and development." (PMID 33456579, 2021). "Vasculogenic mimicry is often observed in the hypoxic tumor microenvironment and is characterized by an increase in HIF-1α/MMP-9/VEGF signaling, the activation of epithelial-mesenchymal transition (EMT)-related proteins such as Twist1, and an upregulation of proinflammatory molecules such as IL-6." (PMID 34359588, 2021). "We identified five genes (ITGA5, MMP9, PTPRN, PTX3, and STX1A) that could significantly affect the OS rate of patients, and the difference between the tumor group and the normal group was statistically significant." (PMID 33767729, 2021). "This hypothesis is based on previous work that highlights PAR1 as the orchestrating receptor of macrophage–tumor cell interactions in PDAC and on the fact that MMP9 has recently been identified as a novel PAR1 agonist." (PMID 33932087, 2021). "Interestingly, two of the genes, MMP9 and FMOD, that both were upregulated in tumor cell/CAF spheroids compared to tumor spheroids were found to have a positive impact on overall survival in HNSCC patients." (PMID 34283070, 2021). "Our data also suggest that CP can indeed increase the expression of MMP-9, and its activity in monotherapy does not result in a statistically significant anti-tumor effect." (PMID 34884588, 2021). "Further bioinformatics analysis revealed that MMP9 and IGFBP1 might act as regulators for monocytes migration and tumor immune." (PMID 33758602, 2021).
tumor (continued). "Then, 27 studies were excluded as they detected MMP2/MMP9 expression in serum (n = 17) or cytosol tumor extracts (n = 1) or in stromal cells (n = 1), investigated mRNA expression (n = 4), duplicated with others (n = 4)." (PMID 33568081, 2021). "The tumor microenvironment is rich in stromal cells, such as fibroblasts, and those cells can be re-programmed due to the endocytosis of tumor-derived extracellular vesicles containing TGF-B1, TGF-B2, IL-6, MMP-2, and MMP-9." (PMID 34898576, 2021). "Thus, MMP9 can liberate active IGF and induce the activation of the IGF receptor pathway to promote tumor growth." (PMID 34113616, 2021). "Additionally, interstitial-space–related genes, such as matrix metalloproteinase 1 (MMP1), MMP9, cathepsin, and zinc finger-binding homeobox 1 (ZEB1), play an important part in tumor metastasis." (PMID 33842351, 2021). "Besides, EMT-related proteins vimentin and MMP9 were up-regulated, and the proteolytic activity of MMP was enhanced in tumor metastasis." (PMID 33672529, 2021). "The digestion of abalone intestine with an in vitro gastrointestinal (GI) digestion system resulted in the identification of two peptides with anti-MMP-2 and anti-MMP-9 activity in human fibrosarcoma cells (HT1080 cells), namely abalone oligopeptide (AOP) and abalone anti-tumor peptide (AATP)." (PMID 33498927, 2021). "However, after the transfection of MMP9‐small interfering RNA(siRNA), MMP9 expression was inhibited and the CCL2‐mediated tumour cell migration was also reduced." (PMID 34464477, 2021). "First, imipramine may inhibit ERK/NF‐κB signalling transduction and thus reduced tumour progression‐related proteins expression, including MGMT, MMP‐2, MMP‐9, uPA, VEGF, Cyclin D1 and XIAP." (PMID 32149465, 2020). "Consistent with the in vitro results, mice injected with ESM-1-overexpressing 4T1 cells exhibited significant increases in tumor volume, lung metastasis, metastasis-related molecules (VEGF, MMP-9, ICAM-1, and VCAM-1), and transcription factors (HIF-1α, phospho-NF-κB, and phospho-STAT-3)." (PMID 32466580, 2020). "It has been reported that cytokines and pro-inflammatory TME promote the phosphorylation of NF-κB and the expression of proliferative (cyclin D1), metastatic (MMP-9, CXCR4) tumor-promoting proteins and inhibit apoptosis (caspase-3), which have a p65-NF-κB binding site in their promoters." (PMID 32708030, 2020). "In summary, the present study demonstrated the anti-tumor effects of MT on the HCC, and MT suppressed HCC progression possibly via regulating proliferation- and migration-related mediators including c-Met, p-AKT, NF-κB, MMP2, and MMP9 in HepG2 cells." (PMID 32117722, 2020). "Conversely, the outcome of their presence could be in favor of tumor progression through releasing VEGF to support angiogenesis and MMP9 to degrade ECM and facilitate the metastasis." (PMID 31256327, 2020). "The median survival was 36 months in patients with MMP-9-positive tumours and 13 months in patients with MMP-9-negative tumours, which indicates that patients with MMP-9-positive tumours may experience tumour metastasis earlier." (PMID 32209138, 2020). "They play significant roles both in tumor progression and tumor suppression, participating in evolving processes of tumorigenesis, metastasis, and angiogenesis by producing various signaling molecules, such as EGF, VEGF, MMP-9, IFNs, ILs, etc." (PMID 32850861, 2020). "MMP-9 also protects insulin-like growth factor (IFG) from inactivation via insulin-like growth factor binding protein (IGFBP), thereby providing growth signals for neighboring tumor cells." (PMID 32825245, 2020). "Furthermore, CAFs support tumor invasion and dissemination by releasing MMPs (e.g., MMP-2 and MMP-9) and help cancer cell proliferation by releasing exosomes, SDF-1, FGF, IL-6, TGF-β, and osteopontin." (PMID 32499786, 2020). "In addition, it plays an important role in tumor cell migration through upregulating MMP2 and MMP9 expression or activating integrin 42-44." (PMID 33173412, 2020).
tumor (continued). "In our study, mRNA levels for VEGF, NFkB, CDKN2a-p16, MMP2, MMP9 genes were increased in the tumor microenvironment from PNT rats, but the results were not significant because of the high cell heterogeneity found between OSCC samples of both groups." (PMID 32499868, 2020). "Indeed, MDSCs produce high levels of MMPs, including MMP2, MMP8, MMP9, MMP13, and MMP14, which by digesting ECM allow tumor cells migration." (PMID 32133298, 2020). "Intraperitoneally administered β-elemene was reported to inhibit in vivo growth and metastasization of C57BL/6 mice carrying B16-F10 melanoma through downregulation of tumor promoting factors such as MMP-2, MMP-9, VEGF, urokinase-type plasminogen activator (uPA) and uPA receptor." (PMID 32948083, 2020). "Furthermore, the levels of the tumor invasion-related proteins MMP-2 and MMP-9 decreased significantly after treatment with hesperetin and DDP, which was reversed by downregulation of PTEN (#P < 0.05)." (PMID 32973533, 2020). "Expression of matrix metalloproteases 2, 9 and 14 (MMP-2, MMP-9, MMP-14), tissue inhibitors of metalloprotease 1 and 2 (TIMP-1, TIMP-2) and vascular endothelial growth factor A (VEGF-A) is involved in tumor invasion and metastasis via extracellular matrix degradation and angiogenesis." (PMID 32669083, 2020). "To understand how oral nanoparticles influence the tumor microenvironment, we investigated anti-metastasis in terms of angiogenesis, EMT, and ECM remodeling via immunohistochemistry (IHC) and detection of the CD31, TGF-β1, and MMP-9 expression levels." (PMID 32473632, 2020). "TGF-β, IL-6, MMP-9 and VEGF in spleen tumours significantly decreased in XYS group." (PMID 33152259, 2020). "We used tissue slides to study the expression of the RSK4, CD44 and MMP-9 proteins in human pRCC and mRCC tumour tissues by immunohistochemistry and found that the RSK4, CD44 and MMP-9 proteins were weakly expressed in pRCC and much more strongly expressed in mRCC tissues." (PMID 32209138, 2020). "Tumor volume, lung metastasis, and tumorigenic molecules (VEGF-A, HIF-1α, MMP-9, ICAM-1, VCAM-1, and phospho-NF-κB and phospho-STAT-3) were significantly induced in mice injected with ESM-1-overexpressing 4T1 cells and greatly enhanced in those injected with ESM-1-overexpressing RT-R-4T1 cells." (PMID 32466580, 2020). "In addition, the abundance of an array of tumor markers, such as PCNA, Ki-67, MMP9, E-cadherin, and N-cardherin were quantified." (PMID 33928018, 2020). "Moreover, tumour progression‐related proteins such as MMP‐2, MMP‐9, uPA, VEGF, Cyclin D1 and XIAP were all decreased by imipramine in U‐87 MG and GBM8401 cells." (PMID 32149465, 2020). "Indeed, TAMs have been proven to promote tumor cell migration and invasion by up-regulating COX-2 and MMP9 expression in osteosarcoma (OS) cells, promoting phosphorylation of STAT3 and inducing epithelial-mesenchymal transformation (EMT)." (PMID 33224886, 2020). "In addition, numerous studies mentioned that MMP‐2 and MMP‐9, which are both regulated by the ERK/MAPK pathway, participate in cancer progression, including tumour growth, angiogenesis, cell invasion and migration." (PMID 32893977, 2020). "However, oral administration of this complex to 4T1 tumor-bearing nude mice strongly inhibited pulmonary metastasis by downregulating CD31, MMP-9, and TGF-β1 in the tumor tissue." (PMID 32473632, 2020). "But it also can stimulate tumor cells to produce MMPs, specifically MMP-2 and MMP-9." (PMID 33178600, 2020). "Besides inhibiting effector function of T cells, M2 macrophages are viewed as obligate partners for tumor cell due to secreting a wide range of bioactive mediators, such as VEGF and MMP-9, to promote tumor migration, invasion, and metastasis." (PMID 33425752, 2020). "Interestingly, we observed that the digestion of NETs with DNase had a minor impact on tumor cell migration as well as in the CXCL8 and MMP9 gene expression." (PMID 32545405, 2020).
tumor (continued). "In addition to mediating immunosuppressive mechanisms, MDSCs also affect the remodeling of the tumor microenvironment and tumor angiogenesis by producing VEGF and MMP9, thereby promoting tumor progression." (PMID 32005273, 2020). "MMP9 and MMP2 are important members of the MMPs family, secreted by neutrophils, macrophages and tumor cells, which participate in the depletion of ECM and play an important role in the vascularization of malignant tumors and the infiltration of tumor cells." (PMID 33292262, 2020). "LINC00312-mediated tumor suppression in ATC cells may occur through suppression of PI3K/AKT signaling pathway and MMP9 gene expression." (PMID 32760219, 2020). "Taken together, these results suggest that Plasmodium infection might reduce MMP-9 and IGF-1 expression in TAMs and tumor tissue and that this effect is responsible for the reduced angiogenesis within tumors." (PMID 32972437, 2020). "Next, we analyzed changes in the expression of vascular endothelial growth factor α (VEGFα) and matrix metalloproteinase 9 (MMP9), which are produced by M2-like TAMs to support tumor growth by inducing neovascularization and modifying the extracellular matrix (ECM)." (PMID 33260160, 2020). "MMP2 and MMP9, the major proteolytic enzymes contributed to ECM degradation, are involved in the process of releasing vascular endothelial growth factor (VEGF), promoting tumor cell migration and invasion." (PMID 32970612, 2020). "The findings in some of these studies have additionally suggested that ZKSCAN3 could modulate several molecules known to play a key role in tumorigenesis and/or tumor progression, such as cyclin D1/D2, EGF, IGF-2, integrin-β4, MMP2/MMP9, NF-κB, and VEGF." (PMID 32824199, 2020). "Several studies have demonstrated that TAMs might produce some angiogenesis-related enzymes, including MMP-2 and MMP-9, which mediate ECM degradation and increase the vascular invasion of tumor cells." (PMID 32972437, 2020). "We detected the levels of three key factors in the tumor group of mice: IL-1β, TNF-α and MMP9." (PMID 32796132, 2020). "Furthermore, CUL7 silencing induced the downregulation of the expression of MMP2 and MMP9, matrix metalloproteinase (MMP) family proteins that play important roles in ECM degradation and in the migration and invasion of tumour cells." (PMID 32252802, 2020). "Because HN4 and HN12 cells are derived from a stage IV tumor, EEOS may regulate their invasiveness by targeting their MMP-2 and MMP-9 activity." (PMID 32102512, 2020). "MMP‐9, as one member of the MMP family, can be used as a controller for tumor neovascularization." (PMID 31901223, 2020). "BCSS of patients with tumours expressing high cytoplasmic MMP9 was significantly shorter than that of the negative/low expression subgroup (p = 0.013; HR = 1.5; 95%CI 1.1–2.0)." (PMID 32445177, 2020). "MMP12 gene expression is not changed, but MMP9 mRNA expression is increased in tumor from CRC patients compared to adjacent non-tumor tissues and controls." (PMID 32171282, 2020). "In addition, OSCC cells with MMP-9/shRNA knockdown and control vector were injected into zebrafish and an OSCC tumor model in zebrafish was established to evaluate invasion and metastasis in vivo." (PMID 32382550, 2020). "A human pancreatic epithelioid carcinoma cell line, Panc I, with lower MMP-2 and MMP-9 expression levels than HT1080 cells was unable to activate the recombinant SeV, demonstrating this system as an efficient tool for delivery to tumor sites where MMP-2 and MMP-9 are overexpressed." (PMID 32466129, 2020). "Notably since MDSCs (like TAMs) secrete MMP9 to facilitate MMP9-dependent cleavage of PD-L1 surface expression anti-PD1 Ab resistance, hypoxia hinders the anti-tumor effects of anti-PD1 Abs." (PMID 32707850, 2020).
tumor (continued). "These cells establish a favorable environment for tumor development by releasing cytokines (IL-6, IL-10 and TGF-β), metalloproteinases (MMP3 and MMP9) and growth factors (HGF, EGF, CTGF and IGF-1), leading to immunomodulation, angiogenesis, invasion, proliferation and tumor cell survival." (PMID 32899449, 2020). "MMP9 exists outside the tumor cells, so the enzyme-triggered deformation of the carrier can occur outside the tumor cells without entering the cells." (PMID 32512936, 2020). "Because of the extensive role of MPs in cell signaling and immune system, inhibition of MPs may also enhance immunotherapy since it was shown that inhibition of MMP-9 and MMP-14 improved T-cell anti-tumor response." (PMID 32466129, 2020). "Our in vivo tumorigenicity model also showed the effects of JAM-B on promoting tumor incidence, the time to tumor appearance, tumor size, tumor weight, and the expression of related factors such as c-Src, E-Cadherin, MMP-2 and MMP-9, which provided necessary support for future mechanistic studies." (PMID 32231730, 2020). "We then assessed MMPs and TIMP3 expression in tumors and adjacent non-tumor colon tissue in CRC patients, MMP12 (P = 0.001), MMP9 (P = 0.0006) and TIMP3 (P = 0.0421) mRNA expression was significantly increased in tumors tissue compared to adjacent non-tumor tissue from CRC patients." (PMID 32171282, 2020). "Of interest, the ability of MMP-9 to favor the spread of tumor cells can also be helped by nonintegrin receptors such as CD44 and CD151, which are coexpressed with MMP-9 by highly invasive cancer cells." (PMID 32630531, 2020). "Treatment with a MMP9-blocking antibody did not affect the tumor growth of subcutaneously implanted PDAC cells, but did enhance gemcitabine and nab-paclitaxel sensitivity when PDAC cells were injected into the peritoneal cavity." (PMID 32325664, 2020). "c-Myc inhibition by treatment with 10058-F4 or transduction of c-Myc by c-Myc/shRNA in human macrophages stimulated by tumor-conditioned medium from PANC-1 (human pancreatic cancer cell line) suppresses expression of protumoral genes (ALOX15, CD206, TGF-β, VEGF, HIF-1α and MMP9)." (PMID 32486098, 2020). "MMP7, MMP13, and MMP10 were significantly upregulated, while MMP12 and MMP9 were downregulated in metastatic tumour samples compared with nonmetastatic tumour samples." (PMID 31996191, 2020). "Two other mAbs targeting MMP-9, AB0041 and AB0046, were found to inhibit tumor growth and metastasis in a surgical orthotopic xenograft model of colorectal carcinoma while reducing the musculoskeletal syndrome usually caused as a side effect of non-selective MMP inhibitors." (PMID 32466129, 2020). "In addition, during tumor invasion and metastasis, MMP-2, MMP-7, and MMP-9, the target genes of Wnt/β-catenin signaling, function to degrade the ECM and basement membrane so that tumor cells can detach, invade, and metastasize." (PMID 33542902, 2020). "In addition, dysregulation of TNF-α production can induce expression of matrix metalloproteinase-9 (MMP-9), which is an enzyme involved in degradation of extracellular matrix and promotion of tumor metastasis." (PMID 32595759, 2020). "KLF5 might inhibit cell invasion by suppressing the transcription of IGF1 in tumor cells and subsequently inhibiting its downstream activation of STAT3/MMP9." (PMID 32546700, 2020). "Scholars have postulated that CD147 and MMP-9 could be unique biomarkers for type-II/III astrocyte-elevated genes and predict tumor progression and prognosis." (PMID 32377273, 2020).